NOTCH1 (notch receptor 1)
Diseases named in the same sentence as NOTCH1 in open-access papers (continued):
Sharing a sentence is not in itself a finding about the gene and the disease.
keloid (9 papers, 2020 to 2023). An irregularly shaped, elevated mark on the skin caused by deposits of excessive amounts of collagen during wound healing. "Contrary to these findings, our previous in vitro study demonstrated that autophagy is disturbed in keloid fibroblasts, leading to the activation of Notch1-mediated NLRP3 inflammasome signaling, which is critical for chronic inflammation." (PMID 36009363, 2022). "Due to aberrant autophagic activity, the levels of Notch1, which is degraded by autophagy, are elevated in keloid fibroblasts, which induces NLRP inflammasome activation." (PMID 36009363, 2022). "In this study, single-cell pathway enrichment analysis revealed that PDGF, NOTCH1, and Eph-Ephrin pathways were enriched in keloid samples compared to controls." (PMID 35054460, 2022). "Notch1 remains active in keloid fibroblasts, particularly in patients who have pruritus or a recent history of keloid-growth." (PMID 33126764, 2020). "Protein levels of Notch1 were significantly increased in keloid fibroblasts than in normal fibroblasts, but the changes were variable between patients." (PMID 33126764, 2020). "We used a strategy to decrease Notch1 levels in keloid fibroblasts by increasing autophagy activity." (PMID 33126764, 2020). "In the present study, NF-κB production increased in keloid fibroblasts but decreased by Notch1 silencing." (PMID 33126764, 2020). "Autophagy enhancers or Notch1 inhibitors can be considered as potential therapeutic targets of keloid and further studies are needed in the future." (PMID 33126764, 2020). "Decreased autophagy activity in keloid can result in Notch1-mediated myofibroblast activation and NLRP3 inflammasome signaling activation which is critical for chronic inflammation." (PMID 33126764, 2020). "Autophagy enhancers and Notch1 inhibitors can be potential treatment targets of keloid by suppressing both NLRP3 inflammasome-induced exaggerated inflammation and scarring." (PMID 33126764, 2020). "The greater increase in Notch1 was seen in patients 2, 3, and 5, who were in the active stage with the recent growth of keloid lesions." (PMID 33126764, 2020). "Autophagy deficiency resulted in upregulation of Notch1, which leads to the pathogenic and persistent myofibroblast activation and NLRP3 inflammasome-induced exaggerated inflammation in keloid fibroblasts." (PMID 33126764, 2020). "Rapamycin, a well-known enhancer of autophagy, significantly decreased the increase of Notch1 levels in keloid fibroblasts." (PMID 33126764, 2020). "Notch1 silencing in keloid fibroblasts by siRNA transfection significantly suppressed increased levels of overall NLRP3 inflammasome complex proteins, NF-kB, and α-smooth muscle actin." (PMID 33126764, 2020). "In addition, human keloid fibroblasts exhibited reduced autophagic flux, resulting in elevated levels of the Notch1 protein, which is degraded by autophagy, and an increase in Notch-NLRP inflammasome formation." (PMID 36009363, 2022). "NOTCH1 inhibitors, and Eph-Ephrin inhibitors, commonly used for cancer, might be of use in the initial stages of keloid." (PMID 35054460, 2022). "In addition, autophagy is involved in NLRP3-inflammasome activation by mediating Notch1 degradation in keloids." (PMID 36009363, 2022). "Furthermore, a recent study reported that KD FBs from subjects affected with active KD (i.e. patients with a recent keloid and complaining keloid pruritus and pain) exhibit a more prominent NOTCH1 activation as compared to KD patients with stable lesions." (PMID 33966637, 2021). "We sought to investigate whether autophagy regulates Notch1 signaling in keloid fibroblasts and determine whether Notch1 signaling might regulate NLRP3 inflammasomes and myofibroblast differentiation." (PMID 33126764, 2020). "Depletion of Notch1 in keloid fibroblasts also suppressed levels of α-SMA and TGF- β3." (PMID 33126764, 2020). "Two of the key pathways in the maintenance of keloids might be NOTCH1 and Eph-Ephrin pathways." (PMID 35054460, 2022).
keloid (continued). "Moreover, they observed that the upregulated Notch1 expression in keloid fibroblasts was matched by reduced autophagic flux in these cells, which normally degrades Notch1: when autophagy was elevated in the keloid fibroblasts by rapamycin treatment, the Notch1 and NLRP3 inflammasome levels dropped." (PMID 35743263, 2022). "Thus, anti-inflammatory treatment targeting Notch1 could be used to reduce extensive fibrosis in keloid." (PMID 33126764, 2020). "Recent studies have identified Notch1 as a novel activator of NLRP3 inflammasome signaling, leading to chronic tissue injury and myofibroblast differentiation in keloid progression." (PMID 37386638, 2023). "The expression of FoxO1 is highly increased in fibroblasts and inflammatory cells in keloid scars and the gene expression levels of several wound growth factors, including FGF2, Notch1, and ADIPOQ, are also decreased in keloid scars." (PMID 34418600, 2021). "Expression levels of Notch1, NLRP3 inflammasome proteins, pro-inflammatory cytokines, and myofibroblast markers in keloid fibroblasts were examined and compared with those in normal fibroblasts." (PMID 33126764, 2020). "Our study demonstrated that Notch1 acts as a novel activator of the NLRP3 inflammasome signaling leading to chronic tissue damage and myofibroblast differentiation in keloid progression." (PMID 33126764, 2020). "Collectively, these results identify Notch1 as a novel activator of NLRP3 inflammasome signaling leading to chronic tissue damage and myofibroblast differentiation in keloid progression." (PMID 33126764, 2020). "Results of the present study suggest that induction of autophagy with rapamycin can attenuate keloidal fibrosis by down-regulating Notch1 and NLRP3 inflammasome in keloid fibroblasts and reduce myofibroblast markers." (PMID 33126764, 2020). "Expression levels of Notch1 and NLRP3 inflammasome in keloid fibroblasts increased compared to those in normal fibroblasts." (PMID 33126764, 2020). "Knockdown of Notch1 with siRNA significantly down-regulated increased levels of NF-κB, NLRP3, ASC, and an intermediate form of caspase-1 in keloid fibroblasts." (PMID 33126764, 2020). "The findings of this study demonstrated that adMSC-Exos inhibited ECM deposition in keloids, which may have been mediated by inhibition of the TGF-β2/Smad3 and Notch-1 signaling pathways." (PMID 35333672, 2022). "In addition, our study showed that rapamycin, an mTOR inhibitor and a well-known autophagy inducer, decreased the protein levels of Notch1, the NLRP3 inflammasome complex, and TGF-β3 in keloid fibroblasts." (PMID 36009363, 2022). "Overexpression of TGF-β3 was observed in keloid fibroblasts than in normal fibroblasts and the expressive patterns of TGF-β3 with/or without Notch1 inhibition were the same as that of α-SMA in the present study." (PMID 33126764, 2020).
osteoporosis (9 papers, 2017 to 2025). A condition of reduced bone mass, with decreased cortical thickness and a decrease in the number and size of the trabeculae of cancellous bone (but normal chemical composition), resulting in increased fracture incidence. "Therefore, we hypothesized that HCG18 might cause abnormal osteogenic differentiation of BMSCs through the miR-30a-5p/Notch1 axis, inhibiting its mediated bone formation and causing osteoporosis." (PMID 33176682, 2020). "This miRNA targets TGIF2 in osteoclasts and NOTCH1 in osteoblasts to ameliorate both post-menopausal and senile osteoporosis." (PMID 39452495, 2024). "Recently, it was reported that miR-210 overexpression may improve the microstructure of bone tissue and reduce bone resorption in ovariectomized rats by activating VEGF/Notch1 signaling, suggesting its protective role in osteoporosis in post-menopausal rats." (PMID 39452495, 2024). "It is suggested that overexpression of miR-210 may ameliorate osteoporosis in menopausal rats by activating the VEGF/ Notch1 signaling pathway." (PMID 37198572, 2023). "High expression of miR-210 may improve the micromorphology of bone tissue and modulate bone formation and resorption in OVX rats by activating the VEGF/Notch1 signaling pathway, thereby alleviating osteoporosis." (PMID 37198572, 2023). "In conclusion, our results indicate that microRNA-139-5p promotes osteogenic differentiation of BMSCs via Wnt/β-catenin signaling pathway by targeting NOTCH1, and moreover, that microRNA-139-5p may have potential clinical applications in osteogenic differentiation of BMSCs or osteoporosis." (PMID 31752063, 2020). "Finally, the hypothesis that osteoblast HIF-1α pathway regulates osteoclastogenesis via IL-33-miR-34a-5p-Notch1 still needs to be confirmed in animal models of osteoporosis, and the clinical relevance of this pathway in osteoporosis or osteopetrosis remains to be elucidated." (PMID 29085370, 2017).
psoriasis (9 papers, 2017 to 2024). An autoimmune condition characterized by red, well-delineated plaques with silvery scales that are usually on the extensor surfaces and scalp. "In this study, the elevated expression of Notch1 and its target gene Hes-1 was demonstrated in peripheral CD4+ T cells of PV patients and positively associated with psoriasis area and severity index, which indicates that Notch1 signaling participates in the development and progress of PV." (PMID 29686529, 2018). "PV patients presented distinct Th17/Treg immune imbalance and highly expressed Notch1 and Hes-1 mRNA levels, which were positively correlated with psoriasis area and severity index (PASI) and the ratios of Th17/Treg and RORγt/Foxp3." (PMID 29686529, 2018). "Upregulated expression of Notch1 has been demonstrated in psoriatic lesions, which can mediate the abnormal differentiation of epidermal keratinocytes and implies the possible role of Notch1 in the pathogenesis of psoriasis." (PMID 29686529, 2018). "In psoriasis patients, there are highly expressed Notch1 and Hes-1 mRNA levels." (PMID 35563285, 2022). "The authors concluded that vascular dysfunction in Psoriasis is mediated by Notch1 signaling route and that this pathway could represent a novel therapeutic target." (PMID 32545758, 2020). "So, all the data suggest that Th17 cells may be an effective regulating target of Notch1 signaling in psoriasis-like skin inflammation." (PMID 29523162, 2018). "Up-regulated expression of Notch1 has been demonstrated in psoriatic lesions, which indicates that Notch1 signaling may participate in the pathogenesis of psoriasis." (PMID 29523162, 2018). "So, our finding indicates that blocking Notch1 signaling by DAPT treatment may contribute to the alleviation of IMQ-induced mouse psoriasis-like skin inflammation." (PMID 29523162, 2018). "Notch1 signaling may contribute to the pathogenesis of psoriasis by microRNA 125b." (PMID 35563285, 2022). "The results of this study highlighted an increased expression of Notch1, DLL4, Hrt-1 (Ring-box protein HRT1) and A-SAA (Acute-phase Serum Amyloid A) in Psoriasis lesional skin if compared to unaffected skin." (PMID 32545758, 2020). "In this study, our aim was to evaluate the possible inhibitory effect of Notch1 signaling inhibitor, γ-secretase inhibitor DAPT, on psoriatic Th17 cell differentiation and function in a mouse model of psoriasis-like skin inflammation." (PMID 29523162, 2018). "In this study, we found that Notch1 inhibition by DAPT can obviously reduce splenic Th17 cell population, mRNA expression of Th17 cell specific transcription factor RORγt, as well as IL-17A mRNA expression and serum concentration in the mouse model of psoriasis-like skin inflammation." (PMID 29523162, 2018).
pulmonary hypertension (9 papers, 2019 to 2025). Increased pressure within the pulmonary circulation due to lung or heart disorder. "In endothelial specific NOTCH1 knockout mice, pulmonary hypertension was more pronounced under hypoxic conditions." (PMID 31380363, 2019). "Importantly, BMPR2 was required for NOTCH1 activation and deletion of endothelial specific Notch1 in transgenic mice exacerbated hypoxia-induced pulmonary hypertension." (PMID 38791441, 2024). "Importantly, BMPR2 was demonstrated to be required for NOTCH1 activation and deletion of endothelial specific Notch1 in transgenic mice exacerbated hypoxia-induced pulmonary hypertension." (PMID 38903104, 2024). "Mutations in NOTCH1 have been identified in familial cases of bicuspid aortic valve, TAA, and aortic dissection and in Adams Oliver syndrome, which includes several congenital heart defects and pulmonary hypertension related to pulmonary vein stenosis." (PMID 32260370, 2020). "As to the correlation between Notch-1 and endothelial cell apoptosis, a recent study has demonstrated that Notch-1 could inhibit endothelial cell apoptosis in pulmonary arterial hypertension via Bcl-2 and Survivin." (PMID 31343412, 2019). "The relation between Notch-1 and HTN has been demonstrated in a recent study that Notch-1 increased proliferation of human pulmonary arterial endothelial cells (hPAECs) in pulmonary arterial hypertension and inhibition of Notch signaling could decrease proliferation and migration of hPAECs." (PMID 31343412, 2019). "While DLL4/NOTCH1 signaling appears to protect the pulmonary vasculature, how and under what conditions DLL4 loss or inhibition contributes to the development of pulmonary hypertension and pathologic vascular remodeling is not understood." (PMID 38791441, 2024).
basal cell carcinoma (8 papers, 2009 to 2024). A carcinoma involving the basal cells. "In a model of Notch1-deficient mice, basal cell carcinoma-like tumors arise spontaneously and were associated with the activation of sonic hedgehog (Shh) signaling." (PMID 30917608, 2019). "Conclusive evidence demonstrating Notch1 acts as a tumor suppressor came from studies in the skin, where loss of both Notch1 alleles led to development of basal cell carcinoma." (PMID 23284900, 2012). "Furthermore, Notch1-deficient animals spontaneously develop basal cell-carcinoma-like tumors associated with upregulation of Shh signaling." (PMID 27929540, 2016). "Conditional deletion of NOTCH1 in the mouse epidermis can lead to basal hyperplasia and basal cell carcinoma." (PMID 34504787, 2021). "Alternatively, in basal cell carcinoma, Notch1 appears to function in a non-cell autonomous manner by mechanisms impacting the tumor microenvironment." (PMID 23284900, 2012).
chronic myeloid leukemia (8 papers, 2015 to 2025). "Notch-1 signaling plays a tumor suppressive role in chronic myeloid leukemia (CML)." (PMID 32197359, 2020). "In Chronic Myeloid Leukaemia (CML), inhibition of NOTCH1 expression in K562 cells induced erythroid maturation of these cells." (PMID 25711903, 2015).
colorectal tumor (8 papers, 2013 to 2023). "It has been reported that miR-139-5p increased 5-FU sensitivity by NOTCH-1 targeting in colorectal tumor cells." (PMID 37051101, 2023). "The inhibition of leptin signaling by the leptin receptor antagonist Allo aca reduced NOTCH1, IL-1R, and ObRb mRNA levels in colorectal tumor tissues." (PMID 38152619, 2023). "Elevated Hey2, Jag1 and Notch1 expression was also observed in whole sWAT fat pads during cachexia in C26 colorectal tumor-bearing mice, showing that this genetic program is not restricted to PDAC." (PMID 37749321, 2023). "Next, we determined the possible association between Notch1 activation and the presence of Paneth cells and LYZ expression in colorectal tumors." (PMID 34831152, 2021). "The blockade of Notch signaling by the γ-secretase inhibitor DAPT significantly reduced NOTCH1, JAGGED1, LEPTIN, ObRb, IL-1β, VEGF-A, and VEGFR1 mRNA levels in colorectal tumor tissues." (PMID 38152619, 2023). "In present study, inhibition of Notch signaling by the γ-secretase inhibitor DAPT significantly reduced NOTCH1, JAGGED1, LEPTIN, ObRb, IL-1β, VEGF-A, and VEGFR1 mRNA levels in colorectal tumor tissues compared to control groups." (PMID 38152619, 2023). "Furthermore, inhibition of IL-1 signaling by Anakinra decreased NOTCH1, JAGGED1, IL-1β, LEPTIN, ObRb, VEGFA, VEGFR1, and VEGFR2 expressions in colorectal tumors." (PMID 38152619, 2023). "In addition, we indicated that downregulation of IL1 signaling by Anakinra reduced NOTCH1 and JAGGED1 expressions in colorectal tumor tissues compared to control groups." (PMID 38152619, 2023). "First, we determined whether Notch, IL-1, and leptin signaling could be involved in the regulation of NOTCH1, JAGGED1, LEPTIN, ObRb, IL-1β, IL-1R, VEGF-A, VEGFR1, and VEGFR2 gene expression in colorectal tumor tissues." (PMID 38152619, 2023). "qRT-PCR analysis revealed that NOTCH3, but not NOTCH1 or 2 mRNA levels are up-regulated in human colorectal tumor tissues compared to adjacent normal tissues." (PMID 24244701, 2013).